CARD9 (caspase recruitment domain family member 9)
Diseases named in the same sentence as CARD9 in open-access papers (continued):
Sharing a sentence is not in itself a finding about the gene and the disease.
acute pancreatitis (4 papers, 2016 to 2020). An acute inflammatory process that leads to necrosis of the pancreatic parenchyma. "We previously reported the up‐regulation of caspase recruitment domain 9 (CARD9) expressions in severe acute pancreatitis (SAP) patients, but little is known about its regulation." (PMID 27957800, 2017). "Previous studies revealed that caspase recruitment domain protein 9 (CARD9) was involved in severe acute pancreatitis (SAP) inflammation and that interfering with its expression in vivo could inhibit inflammation." (PMID 32790017, 2020). "Thereby, it is unknown whether Card9 adaptor molecule is required for the early course of acute pancreatitis without microbial infection." (PMID 26893103, 2016).
aspergillosis (4 papers, 2015 to 2023). Aspergillosis is an infection, growth, or allergic response caused by the Aspergillus fungus. "This study paves the way to elucidate immunological mechanisms underlying CARD9 deficiency and aspergillosis." (PMID 37881270, 2023). "In stark contrast to this partial dependency on Card9 for neutrophil recruitment during pulmonary aspergillosis, we show here that Card9 deficiency almost abolishes neutrophil recruitment to the CNS throughout the entire course of C. albicans infection." (PMID 26679537, 2015).
B cell lymphoma (4 papers, 2018 to 2023). "This is the first report on ectopic expression and function of CARD9 in an aggressive B-cell lymphoma." (PMID 35158799, 2022). "In our study, we demonstrated for the first time the expression of CARD9 in an aggressive B-cell lymphoma." (PMID 35158799, 2022). "CARD9 is an upstream activator of BCL10 and NF-kappaB signaling, which is important to B cell lymphomas of mucosa-associated lymphoid tissue." (PMID 30723747, 2019). "Namely, CARD9 is a marker of tumor progression and poor prognosis in hepatocarcinoma (HCC), B cell lymphoma, and clear cell renal carcinoma and promotes metastatization activating metastasis-associated macrophages (MAM)." (PMID 29871612, 2018).
cardiac ischemia (4 papers, 2022 to 2024). "In myocardial ischemia/reperfusion injury, CARD9 protects the myocardium by interacting with the autophagy negative regulator Rubicon to restore autophagic flux." (PMID 35733381, 2022).
COVID-19 (4 papers, 2020 to 2023). A disease caused by infection with severe acute respiratory syndrome coronavirus 2. "We have already reported that the impaired tryptophan metabolism in patients with severe COVID-19 is associated with decreased expression of ACE2, AHR, CARD9 in the ileal mucosa." (PMID 39131552, 2023). "Spike COVID-19 protein stimulation also leads to increased gene expression of CARD9, and CCL5." (PMID 34571855, 2021). "Among our results, several immune-related pathways including those activated by Fc-epsilon-related signaling (LYN and PI3K), NIK/NF-κB (ub, CUL1, SKP1, proteasome, and NFKB2), and via C-type lectin receptor pathways (PTPN11 and CARD9) were enriched in the COVID-19 lungs." (PMID 33060566, 2020). "The expression of genes involved in tryptophan metabolism, including ACE2, AHR, CARD9, and IL22, was downregulated in the ileum of critical COVID-19 patients who required a colonoscopy." (PMID 36035409, 2022). "SARS-CoV-2-infected PBMC from COVID-19 presented a significantly higher expression of genes related to virus entry (cellular SARS-CoV-2 receptor ACE2) and apoptosis (CARD6, and CARD9); reinforcing CD8+ T cells CD95+ immunophenotyping." (PMID 34571855, 2021). "The expression of ACE2, AHR, and CARD9 was decreased in the ileum of the COVID-19 patients, and the expression of IL22, a cytokine regulated by aryl hydrocarbon receptor (AhR), was also decreased in the ileum of the COVID-19 patients." (PMID 36035409, 2022). "In addition, the mechanism of gastrointestinal damage in patients with COVID-19 may involve impaired tryptophan metabolism due to the decreased expression of ACE2, AHR, and CARD9 in the small intestinal mucosa." (PMID 36035409, 2022).
dermatitis (4 papers, 2016 to 2023). An inflammatory process affecting the skin. "We have also tested the effect of CARD9 deficiency on dermatitis triggered by systemic administration of antibodies against collagen VII (a mouse model of the human blistering skin disease epidermolysis bullosa acquisita)." (PMID 27032818, 2016).
Hyperglycemia (4 papers, 2017 to 2026). An increased concentration of glucose in the blood. "Among the four BMDM groups, those receiving BTX‐stimulated Card9−/− BMDMs exhibited the most pronounced early‐onset hyperglycemia." (PMID 41243316, 2026). "Given that hyperglycemia induces chronic inflammation as a causative factor of cardiac remodeling, the expression levels of inflammatory markers, including p-P38, p38, TNF-α, IL-1β, CARD9, and BCL10, were examined by Western blot." (PMID 28272348, 2017). "Notably, Card9 deficiency alone did not induce hyperglycemia in the absence of STZ treatment." (PMID 41243316, 2026). "Interestingly, in contrast to data accrued in CARD9 expression studies, co-provision of either TSA or SAHA significantly increased the expression of PKCδ under basal (LG) conditions without significantly exerting any effects on its expression induced under duress of hyperglycemia." (PMID 37958977, 2023).
Insulin resistance (4 papers, 2018 to 2025). Increased resistance towards insulin, that is, diminished effectiveness of insulin in reducing blood glucose levels. "Our previous study have shown that CARD9 deficiency attenuated HFD‐induced insulin resistance, glucose intolerance and PM‐derived inflammatory cytokines." (PMID 35962606, 2022). "The present study suggested that CARD9 knockout may potentially ameliorate diet‐induced inflammation, insulin resistance, metabolic disorders and T2D either by inhibiting the NF‐κB and MAPKs signalling pathway or by improving insulin action and enhancing the energy metabolism." (PMID 29575791, 2018).
lung adenocarcinoma (4 papers, 2024 to 2025). A carcinoma that arises from the lung and is characterized by the presence of malignant glandular epithelial cells. "This oral commensal has previously been linked to immunosuppression in lung adenocarcinoma through the β-glucan/Dectin-1/CARD9/IL-1β axis." (PMID 40391887, 2025). "A study on the mycobiome in lung adenocarcinoma has shown that Aspergillus sydowii stimulates the production of the key molecule IL-1β through the b-glucan-mediated Dectin-1/CARD9 signaling pathway, thereby inducing MDSCs differentiation and promoting the formation of a tumor-suppressive TIME." (PMID 39408814, 2024). "In a separate study, the identical SunTag system (dCas9-multiGCN4 + ScFv-TET1CD) was employed to induce the expression of CARD9, SH3BP2, and CNKSR1 in A549 and 1–87 lung adenocarcinoma cell lines." (PMID 40650152, 2025).
ulcerative colitis (4 papers, 2013 to 2024). An inflammatory bowel disease involving the mucosal surface of the large intestine and rectum. "In germ-free mice, the introduction of M. restricta exacerbated intestinal inflammation by activating Card9 signaling through the Dectin-2 receptor, thereby intensifying the severity of ulcerative colitis." (PMID 38397900, 2024).
AIDS (3 papers, 2021 to 2025). A syndrome resulting from the acquired deficiency of cellular immunity caused by the human immunodeficiency virus (HIV). "Therefore, we tested Clec7a−/−Fcer1g−/− compared with Card9−/− and wild-type (WT) mice in the mouse CD4-deficient PCP model, which mimics CD4 impairment during AIDS." (PMID 39745390, 2025).
Autoimmunity (3 papers, 2012 to 2023). The occurrence of an immune reaction against the organism's own cells or tissues. "Th17 cell responses are often associated with autoimmunity and polymorphisms in Card9 are recurrently detected in human inflammatory diseases." (PMID 22265677, 2012). "Downstream of TLRs, the adaptor proteins MyD88 and CARD9 and the transcription factor IRF5 generate hyperactivated signaling in LynKO myeloid cells and drive autoimmunity in LynKO mice." (PMID 37265689, 2023).
diabetes (3 papers, 2016 to 2026). "Both models consistently demonstrated that CARD9 deficiency accelerated diabetes onset and markedly worsened sympathetic nerve loss." (PMID 41243316, 2026). "Card9 silencing markedly increased diabetes incidence and reduced survival, accompanied by decreased insulin secretion." (PMID 41243316, 2026). "Based on these data, we propose that targeting the appropriate HDACs, which mediate the expression (and function) of CARD9, might be the next step to further enhance our current understanding of the roles of CARD9 in islet dysfunction under metabolic stress and diabetes." (PMID 37958977, 2023).
disseminated candidiasis (3 papers, 2015 to 2025). Systemic candidiasis occurs when Candida yeast enters the bloodstream and may spread (becoming disseminated candidiasis) to other organs, including the central nervous system, kidneys, liver, bones, muscles, joints, spleen, or eyes. "However, the myeloid cell types and molecular mechanisms implicated in CARD9 protecting against disseminated candidiasis remain wholly elusive." (PMID 38566195, 2024). "High-dose models of disseminated candidiasis in Card9–/– mice suggest that impaired neutrophil recruitment to the brain underlies disease." (PMID 40424070, 2025). "Conclusively, these data confirm that mitochondrial OXPHOS is involved in the augmented acute kidney injury and ferroptosis induced by CARD9 deletion during disseminated candidiasis." (PMID 38566195, 2024). "Caspase Recruitment Domain-containing protein 9 (CARD9) expressed in myeloid cells has been demonstrated to play an antifungal immunity role in protecting against disseminated candidiasis." (PMID 38566195, 2024). "In conclusion, our work demonstrates that CARD9 ablation exacerbates acute kidney injury in disseminated candidiasis by enhancing ferroptosis of MDSCs, which is attributed to the lower expression of SLC7A11." (PMID 38566195, 2024). "The molecular mechanism by which CARD9 ablation promotes acute kidney injury in disseminated candidiasis was identified by RNA-sequencing analysis." (PMID 38566195, 2024). "In conclusion, our findings manifest that CARD9 plays an essential role in suppressing acute kidney injury and ferroptosis during disseminated candidiasis." (PMID 38566195, 2024). "The role of CARD9 ablation in exacerbating disseminated candidiasis was determined in vivo and in vitro." (PMID 38566195, 2024). "Y91HKI mice phenocopy Card9–/– mice during disseminated candidiasis in vivo." (PMID 40424070, 2025). "Since lethality during disseminated candidiasis is correlated to kidney fungal burden in WT mice, and Card9–/– mice fail to control fungal growth not only in the kidneys but also in the brain, we next compared the kinetics of tissue fungal burden in both kidney and brain." (PMID 40424070, 2025). "Consistent with our in vitro results, activation of OXPHOS by α-KG promotes acute kidney injury and ferroptosis, whereas inhibition of OXPHOS by metformin reverses acute kidney injury and ferroptosis exacerbated by CARD9 ablation during disseminated candidiasis." (PMID 38566195, 2024). "Finally, pharmacological inhibition of mitochondrial OXPHOS or ferroptosis significantly increased the number of MDSCs in the kidneys to augment host antifungal immunity, thereby attenuating ferroptosis and acute kidney injury exacerbated by CARD9 ablation during disseminated candidiasis." (PMID 38566195, 2024). "To elucidate whether mitochondrial OXPHOS is implicated in the enhancement of acute kidney injury and ferroptosis induced by CARD9 deletion during disseminated candidiasis, we established invasive C. tropicalis infection model by using WT mice and Card9−/− mice." (PMID 38566195, 2024).
hyper-IgE syndrome (3 papers, 2010 to 2024). A condition that is characterized by elevated serum IgE, dermatitis, and respiratory infections. "In the second Ion Torrent negative patient (PID82) presenting an atypical HyperIgE syndrome, Haloplex detected two rare homozygous mutations in MYD88 and CARD9 genes, which were not included in the Ion Torrent panels (1 and 2)." (PMID 31031743, 2019).
Hypertension (3 papers, 2016 to 2025). The presence of chronic increased pressure in the systemic arterial system. "Moreover, deletion of CARD9 and BCL10 decreased hypertension-induced cardiac fibrosis and electrical remodeling, and reduced NF-κB activity 34,35." (PMID 39897024, 2025).
lung carcinoma (3 papers, 2020 to 2022). "CARD9 also protected against lung cancer development by reducing the expansion of MDSCs and indoleamine 2,3-dioxygenase (IDO) production." (PMID 34480018, 2021). "In summary, the current evidence seems to favor an anti-cancer role for CARD9 in lung cancer." (PMID 35910636, 2022). "Meanwhile, Card9 relieved the incidence of lung cancer by reducing IDO production in MDSCs." (PMID 34480018, 2021). "Collectively, our data demonstrated the first time that GLP induced the differentiation of MDSCs and inhibited the accumulation of MDSCs via CARD9-NF-κB-IDO pathway, thus prevented lung cancer development." (PMID 32530032, 2020). "Recent studies have confirmed that CARD9 may play a crucial role in a variety of cancers, particularly CRC and lung cancer." (PMID 35910636, 2022).
neutropenia (3 papers, 2015 to 2016). A decrease in the number of neutrophils found in the blood. "We investigated the underlying mechanisms for the CNS-specific neutropenia observed in our CARD9-deficient patient and Card9−∕− animals." (PMID 27092298, 2016). "Thus, genetic variants in CARD9- or in MyD88-dependent signaling pathways may predispose to IA only in the setting of innate immune damage (e.g. in patients with neutropenia or in patients that receive corticosteroids)." (PMID 25621893, 2015). "In our CARD9-deficient patient, this CNS-specific neutropenia could not be explained by a decrease in circulating neutrophils or neutrophil survival, nor a cell-intrinsic chemotaxis defect." (PMID 26679537, 2015).
ovarian carcinoma (3 papers, 2021 to 2025). A malignant neoplasm originating from the surface ovarian epithelium. "As a result, CARD9 is proposed to be associated with the onset and progression of ovarian cancer." (PMID 36443670, 2022). "CARD9, a key regulator of caspase activation and NF-κB signaling, was abnormally upregulated in ovarian cancer tissues and cells, where its knockdown led to reduced cell proliferation and enhanced cisplatin sensitivity." (PMID 39859203, 2025). "GEPIA analysis demonstrated that HOXB5 was also highly expressed in ovarian cancer tissues and positively correlated with CARD9 according to Spearman correlation." (PMID 36443670, 2022). "In conclusion, this study revealed that CARD9 is involved in ovarian cancer cell proliferation, migration, and cisplatin sensitivity via NF-κB signaling after transcriptional activation by HOXB5." (PMID 36443670, 2022). "So we actually collected ovarian cancer and adjacent tissue samples, and analyzed the level of CARD9 by RT-qPCR and immunoblotting, respectively." (PMID 36443670, 2022). "The regulatory role of CARD9-dependent NF-κB signaling in ovarian cancer is disclosed, which lay the foundation for follow-up research." (PMID 36443670, 2022). "Herein, CARD9 expression was found to be up-regulated in ovarian cancer using the Gene Expression Profiling Interactive Analysis (GEPIA) database analysis (gepia.cancer-pku.cn), and high expression was associated with a poor prognosis." (PMID 36443670, 2022). "From the presented results, it was shown that CARD9 was indeed abnormally upregulated in ovarian cancer tissue." (PMID 36443670, 2022). "According to the GEPIA database, the level of CARD9 is significantly elevated in ovarian cancer and its high level is positively correlated with poor prognosis." (PMID 36443670, 2022). "Together, CARD9 is involved in ovarian cancer cell proliferation, migration, and cisplatin sensitivity via NF-κB signaling after transcriptional activation by HOXB5." (PMID 36443670, 2022). "The levels of CARD9 were detected in acquired ovarian cancer tissues and cell lines." (PMID 36443670, 2022). "As a consequence, it is speculated that CARD9 may be involved in cisplatin sensitivity of ovarian cancer via NF-κB." (PMID 36443670, 2022). "Furthermore, according to research, RAD50 double strand break repair protein-mediated NF-κB pathway activation in ovarian cancer is dependent on CARD9, and interfering with CARD9 reduces ovarian cancer cell migration." (PMID 36443670, 2022). "This indicated that CARD9 was positively regulated by HOXB5 in ovarian cancer cells." (PMID 36443670, 2022). "To this end, we performed immunoprecipitation (IP)–western blot to test whether Rad50 can interact with CARD9 in ovarian cancer cells." (PMID 34734468, 2021). "To verify whether Rad50‐mediated activation of NF‐κB pathway is CARD9 dependent, we knocked down CARD9 in Rad50‐overexpressed ovarian cancer cell lines and found that knockdown of CARD9 significantly reversed Rad50‐induced migration activities." (PMID 34734468, 2021). "Therefore, we identified CARD9 as an interacting protein of Rad50 in ovarian cancer cells and Rad50‐mediated activation of NF‐κB pathway is CARD9 dependent." (PMID 34734468, 2021). "Moreover, we identified CARD9 as an interacting protein of Rad50 in ovarian cancer cells and the activation of NF‐κB pathway by Rad50 is CARD9 dependent." (PMID 34734468, 2021). "Furthermore, we verified CARD9 as a specific interacting protein of Rad50 in ovarian cancer cells and Rad50‐mediated activation of NF‐κB pathway is CARD9 dependent." (PMID 34734468, 2021). "The major objective of this work was to define the functions of CARD9 and HOXB5 in ovarian cancer cell proliferation, migration, and cisplatin sensitivity." (PMID 36443670, 2022). "Caspase recruitment domain family member 9 (CARD9) and homeobox B5 (HOXB5) are related and both are upregulated in ovarian cancer." (PMID 36443670, 2022).
ovarian carcinoma (continued). "Future studies will be required to explore the molecular cooperation between Rad50 and CARD9 in promoting proliferation/invasion and inducing EMT in ovarian cancer." (PMID 34734468, 2021). "Therefore, we explore the roles of CARD9 and HOXB5 in ovarian cancer cells in relation to cisplatin sensitivity." (PMID 36443670, 2022). "CARD9 was detected in the immunoprecipitates with anti‐Rad50 antibody, but not with the control mouse IgG in HEK293T and ovarian cancer cell lines." (PMID 34734468, 2021).
pancreatitis (3 papers, 2016 to 2020). Inflammation of the pancreas. "In summary, this is the first report that siRNA silencing of CARD9 provides protection against sodium taurocholate‐induced pancreatitis in rats." (PMID 27957800, 2017). "Accompanied with the severity of pancreatitis, CARD9 mRNA in the SAP group significantly increased after three hours and reached a peak at 12 hrs." (PMID 27957800, 2017). "CARD9 was overexpressed in SAP rats, which correlated with the severity of pancreatitis." (PMID 27957800, 2017).
parasitic infections (3 papers, 2022 to 2024). "Previous publications have confirmed that CARD9 plays a crucial role in fungal, bacterial, viral, and parasitic infections." (PMID 36439825, 2022). "CARD9 is a critical adapter of C‐type lectin receptors (CLRs), such as Dectin‐1 (Clec7a), Dectin‐2 (Clec6a) and Mincle (Clec4e), in response to fungal, viral, bacterial and parasitic infections." (PMID 39118286, 2024).